FOXF1 (forkhead box F1)
Diseases named in the same sentence as FOXF1 in open-access papers (continued):
Sharing a sentence is not in itself a finding about the gene and the disease.
lung carcinoma (continued). "As per our previous study, the reprogrammed inhibition of FOXF1 in the fusion cell lines (MSCs with lung cancer cells) led to an inhibited p21 expression, which resulted in their accelerated grow rate." (PMID 32370197, 2020). "FENDRR (FOXF1 adjacent non-coding developmental regulatory RNA) is also one of the most well-known lncRNAs that functions to inhibit tumor including lung cancer." (PMID 31374807, 2019). "Some of these lncRNAs like FENDRR (FOXF1 adjacent non-coding developmental regulatory RNA), UCA1(urothelial cancer associated 1) have been reported to play roles in lung cancer development." (PMID 31374807, 2019). "Up-regulated FOXF1 has anti-malignant effects of mesenchymal stem cell fusion-induced reprogramming on lung cancer cells." (PMID 28881680, 2017). "The analysis of fusion progeny between mesenchymal stem cells and lung cancer cells has recently demonstrated that FOXF1 significantly reduced the growth rate and expression levels of proteins regulating the cell cycle." (PMID 26462560, 2015). "Transcriptome profiles also revealed that lung cancer cells are reprogrammed to a more benign state through restoring the expression of FOXF1, a putative reprogramming mediator." (PMID 25237908, 2014). "Collectively, FOXF1 plays a regulatory role in mediating the reprogramming effects of MSC fusion on lung cancer cells." (PMID 25237908, 2014). "The anti-malignant effects of MSC fusion-induced reprogramming on lung cancer cells were accomplished by complementation of genetic defects, including up-regulation of FOXF1 and p21 as well as restoration of normal terminal differentiation pathways." (PMID 25237908, 2014). "As depletion of Foxf1 in endothelial cells accelerated cancer progression in orthotopic and urethane-induced lung cancer models, we next tested whether increasing the Foxf1 expression in ECs would prevent lung tumor progression and metastasis." (PMID 38589650, 2024). "FOXF1 is upregulated in lung cancer CAFs by the hedgehog signaling pathway, which might be related to their ability to modulate the inflammatory response and stimulate tumor cell growth, invasion, angiogenesis, and metastasis." (PMID 36661515, 2023). "FOXF1 is negatively regulated in eight sets of lung cancer data and in the PAH set." (PMID 36101460, 2022). "Expression of FOXF1 in lung cancer fibroblast promotes the cancer invasion and spread." (PMID 34257615, 2021). "Hence, we aimed to investigate outcomes of transcriptional dependencies using the FOXF1 gene in lung cancer." (PMID 32370197, 2020). "Alterations in the coding sequence have rarely been found in lung cancer, indicating that mechanism of FENDRR and FOXF1 inactivation could be, among others, loss of heterozygosity (LOH) and promoter hypermethylation." (PMID 32284793, 2020). "This evidence corresponds to our study where highly expressed FOXF1 could inhibit cell migration in lung cancer, possibly through upregulation of E-cadherin and TIMP3." (PMID 32370197, 2020). "However, the methylation analysis showed a relatively high incidence of FOXF1 methylation among lung cancer patients and lung tumoral cell lines." (PMID 32284793, 2020). "Our results, however, showed that FOXF1 expression could by silenced by promoter methylation also in lung cancer." (PMID 32284793, 2020). "Previously, our studies identified FOXF1 as a putative tumor suppressor, which could mediate mesenchymal stem cell fusion-induced reprogramming of lung cancer cells to a more benign state." (PMID 32370197, 2020). "Interestingly, treatment with demethylating agent 5-aza-deoxycytidine (5-Aza) of lung cancer cell lines didn't produce any change in methylation of FOXF1 promoter." (PMID 32284793, 2020). "Sequence analysis detected hypermethylation of FOXF1 promoter in 2 of 5 cell lines (H441 and H838), indicating that hypermethilation of FOXF1 promoter could mediate the downregulation of FOXF1 in lung cancer." (PMID 32284793, 2020).
lung carcinoma (continued). "We found that FOXF1 was downregulated in lung cancer tissues and cancer cell lines." (PMID 32370197, 2020). "However, in this study, we reported an inhibited proliferation of highly expressing FOXF1 lung cancer cells compared to their relatively low-expression counterpart, which reveals the anti-proliferative activities induced by FOXF1." (PMID 32370197, 2020). "Therefore, we also evaluated the other cancerous characteristics of highly expressing FOXF1 lung cancer cell lines, H441-FOXF1H and H1299-FOXF1H." (PMID 32370197, 2020). "Previously, we identified forkhead box F1 (FOXF1) as a reprogramming mediator which leads to stemnesss when mesenchymal stem cells fuse with lung cancer cells, and we now examine its effect on lung cancer through establishing lowly and highly expressing FOXF1 NSCLC engineered cell lines." (PMID 32370197, 2020). "Additionally, FOXF1 expression in lung cancer cell lines (H441 and H1299) was compared with normal lung cell lines (MRC5 and BEAS-2B)." (PMID 32370197, 2020). "Furthermore, we created a highly expressing FOXF1 lung cancer cell line (FOXF1H) through lentiviral transduction of lowly expressed FOXF1 parental cell lines (FOXF1L) and comparatively characterized their cell proliferation and migration ability." (PMID 32370197, 2020). "Hence, in addition to the reprogramming toward stemness, FOXF1 contributes to the anti-malignant effects of MSC fusion on lung cancer cells by regulating the expression of p21." (PMID 25237908, 2014). "FOXF1 (forkhead box F1) is a stemness reprogramming mediator (when mesenchymal stem cells fuse with lung cancer cells) which is also related to the inhibition of cell growth, proliferation, and migration; therefore, it must be downregulated in lung cancer cells." (PMID 36661515, 2023). "Therefore, we infer that FOXF1 modulates lung cancer growth via regulating p21." (PMID 32370197, 2020). "This indicates that FOXF1 may promote pronounced cell-cycle arrest in the G1 phase of lung cancer." (PMID 32370197, 2020). "The anti-malignant effects of MSC fusion-induced reprogramming on lung cancer cells were accomplished by complementation of tumorigenic defects, including restoration of p21 function and normal terminal differentiation pathways as well as up-regulation of FOXF1, a putative tumor suppressor." (PMID 25237908, 2014). "We have demonstrated that maintaining FOXF1/FZD4 signaling in pulmonary EC via genetic or gene therapy is beneficial to normalize tumor vessels and inhibit lung cancer progression." (PMID 38589650, 2024). "The CCPs formed between lung cancer and PAH have FOXM1 and FOXF1 co-expressed with the most frequent DEGs in microarrays and RNA-Seq datasets, respectively." (PMID 36661515, 2023). "FoxF1, a downstream effector of HH signaling, stimulates the secretions of HGF and FGF2 by lung cancer fibroblasts, promoting lung cancer cell growth and migration in vivo." (PMID 35433472, 2022). "For this reason, we decided to analyze the methylation status of the FOXF1 promoter experimentally by pyrosequencing of bisulfite-modified DNA and MSP analysis in A549, H441, H661, H838 and H460 human lung cancer cell lines." (PMID 32284793, 2020). "Thus, FOXF1 could be a potential therapeutic candidate for lung cancer." (PMID 32370197, 2020). "Based on mRNA expression analysis that revealed a positive correlation between FENDRR and FOXF1 for lung cancer, we explored the possible functional relationship between FENDRR and FOXF1 using luciferase assays." (PMID 32284793, 2020). "Conclusively, highly expressing FOXF1 inhibited NSCLC growth via activating tumor suppressor p21 and G1 cell-cycle arrest, thus offering a potentially novel therapeutic strategy for lung cancer." (PMID 32370197, 2020). "In the present study, some of the mostly connected mRNAs were already reported to be correlated with lung cancer, including SOX2, FOXF1, PTK2B and VHL." (PMID 26159226, 2015).
lung carcinoma (continued). "Co-expression network construct indicated that some of the mostly connected mRNAs and TFs were previously reported to be dysregulated in lung cancer, including SOX2, FOXF1, PTK2B, XRCC2, AML-1a (RUNX1), GATA-2 and MZF1." (PMID 26159226, 2015). "Two of the most frequently dysregulated transcription factors are co-expressed in lung cancer and PAH (FOXM1 and FOXF1), while the other six frequently deregulated transcription factors are co-expressed only in lung cancer (TCF21, SOX17, TAL1, LMO2, KLF2, and TBX4)." (PMID 36661515, 2023). "HOXC6 and RFX2 are also deregulated in eight sets of lung cancer as FOXF1 and none of the other types of cancer." (PMID 36101460, 2022). "The results indicated that expression of FENDRR and FOXF1 in lung cancer tissues was significantly lower than those observed in adjacent normal tissues, suggesting the potential of using FENDRR and FOXF1 to successfully distinguish cancerous from normal tissues." (PMID 32284793, 2020). "Thus, much more work is still required to determine the detailed mechanisms it functions in lung cancer and the potentiality of FENDRR and FOXF1 as therapeutic targets for lung cancer." (PMID 32284793, 2020). "Furthermore, TFAP2A was confirmed to inhibit the development and progression of lung cancer, as well as the disordered pathway of FENDRR (FOXF1 adjacent non-coding development regulatory RNA)." (PMID 32294625, 2020). "Specifically, FOXF1 could regulate the transcriptional activity of CDH1 by acting on its FOXF1-binding site, eventually contributing to cell migration and invasiveness in lung cancer." (PMID 32370197, 2020). "Moreover, FOXF1 is also co-expressed in the CCP of the LC RNA-Seq datasets, along with seven of the most frequently dysregulated TFs (FOXM1, SOX17, TAL1, TCF21, TBX4, LMO2, and KLF2), suggesting its importance as a regulator of gene expression during lung cancer progression." (PMID 36661515, 2023). "FOXF1 and GATA6 stand out since they are deregulated in the majority, eight and seven, respectively, of the ten sets of lung cancer, in none of the others types of cancer, and in the PAH set, which suggests their association with the establishment of tumor pathology in the lung." (PMID 36101460, 2022).
colorectal cancer (12 papers, 2013 to 2025). A primary or metastatic malignant neoplasm that affects the colon or rectum. "FOXF1 expression has also been associated with high grade and advanced stage colorectal cancer." (PMID 34257615, 2021). "Similarly, cytoplasmic localization of the transcription factor FOXF1 is positively associated with histologic grade, depth of invasion, and lymphatic metastasis of colorectal carcinoma." (PMID 24223206, 2013). "Concerning cytoplasmic positivity of FOXF1, the cytoplasmic vs. nuclear localization of this transcription factor has been described to correlate with progression of colorectal cancer." (PMID 34257615, 2021). "In a seminal study, FOXF1 was suggested as a potential prognostic marker due to its correlation with malignancy and metastasis of colorectal cancer." (PMID 32370197, 2020). "Moreover, FOXF1 has been described to play a significant role in cancerogenesis and cancer promoting molecular processes in colorectal cancer." (PMID 34257615, 2021). "Genes with a broad H3K4me3 domain in normal CCD 841 CoN cells but not in colorectal cancer cells included FOXF1 adjacent non-coding developmental regulatory RNA (FENDRR) and Meis Homeobox 1 (MEIS1)." (PMID 40141189, 2025).
pulmonary fibrosis (12 papers, 2019 to 2025). Chronic progressive interstitial lung disorder characterized by the replacement of the lung tissue by connective tissue, leading to progressive dyspnea, respiratory failure, or right heart failure. "In a recent study focusing on fibrosis-associated endothelial cells, our group found that Foxf1 is one of the most downregulated genes in the bleomycin-injured mouse model of pulmonary fibrosis." (PMID 38274049, 2023). "FOXF1-deficient endothelial cells were associated with accelerated lung fibrosis and inflammation, and lung delivery of FOXF1 cDNA via nanoparticles attenuated lung fibrosis development in mice treated with bleomycin, showing the potential of this finding as a treatment strategy in IPF." (PMID 38686182, 2024). "Thus, FOXF1 deficiency in murine endothelial cells exacerbates bleomycin-induced pulmonary fibrosis." (PMID 37137915, 2023). "However, Foxf1 aberrant expression has been linked to alteration in downstream pathways in lung fibroblasts in idiopathic pulmonary fibrosis (IPF)." (PMID 30739275, 2019). "Our results support the use of FOXF1-activating therapies for vascular normalization in pulmonary fibrosis." (PMID 37137915, 2023). "Focusing on FOXF1, we found that FOXF1 is decreased in EC within human idiopathic pulmonary fibrosis (IPF) and mouse bleomycin-injured lungs." (PMID 37137915, 2023). "In the present study, we used single cell RNA-sequencing and mouse genetics to demonstrate that EC regulate pulmonary fibrosis through FOXF1/R-Ras-dependent inhibition of profibrotic mediators." (PMID 37137915, 2023). "Here, the authors show that FOXF1/R-Ras signalling in EC inhibits profibrotic mediators and that ECspecific nanoparticle FOXF1 gene therapy decreases lung fibrosis in mice." (PMID 37137915, 2023). "Our studies support the notion that increasing expression of FOXF1 in endothelial cells through nanoparticle delivery of Foxf1 cDNA can be considered to alleviate pulmonary fibrosis." (PMID 37137915, 2023). "To determine the role of FOXF1 in endothelial cells during pulmonary fibrosis, we used mice in which the Foxf1 gene was specifically deleted in endothelial cells using Pdgfb-CreER transgene, which does not target other cell types in the adult lung." (PMID 37137915, 2023). "Altogether, overexpression of FOXF1 in endothelial cells either prior to or after bleomycin injury attenuates pulmonary fibrosis and improves mice survival after the injury." (PMID 37137915, 2023). "Altogether, nanoparticle delivery of Foxf1 cDNA into endothelial cells on the day of bleomycin injury or during fibrotic stage after the injury inhibits pulmonary fibrosis and improves mice survival." (PMID 37137915, 2023). "Transgenic overexpression or endothelial-specific nanoparticle delivery of Foxf1 cDNA decreased pulmonary fibrosis in bleomycin-injured mice." (PMID 37137915, 2023). "Foxf1 was recently reported to inhibit myofibroblast invasion, collagen secretion, and pulmonary fibrosis in a bleomycin-induced fibrosis mouse model." (PMID 35980387, 2022). "Thus, restoring or increasing Foxf1 levels in endothelial cells should be considered to alleviate pulmonary fibrosis." (PMID 38274049, 2023). "Next, we assessed whether increasing endothelial FOXF1 in already established lung fibrosis will improve the outcomes." (PMID 37137915, 2023). "We next examined expression of FOXF1 in endothelial cells in a mouse model of pulmonary fibrosis." (PMID 37137915, 2023). "Thus, overexpression of FOXF1 in endothelial cells prior to bleomycin injury attenuates pulmonary fibrosis and improves survival after bleomycin-induced lung injury." (PMID 37137915, 2023). "Since genetic overexpression of Foxf1 in endothelial cells attenuated pulmonary fibrosis, we next tested whether nanoparticle delivery of Foxf1 cDNA into endothelial cells can be a therapeutic approach to inhibit lung fibrosis." (PMID 37137915, 2023).
pulmonary fibrosis (continued). "Since conditional deletion of FOXF1 in endothelial cells increased pulmonary fibrosis after chronic bleomycin injury, we examined whether overexpression of FOXF1 in endothelial cells was sufficient to inhibit lung fibrosis." (PMID 37137915, 2023). "FOXF1, a member of the forkhead box family of transcription factors, has previously been shown to be critical for lung development, lung regeneration after partial pneumonectomy, and the inhibition of bleomycin-induced pulmonary fibrosis." (PMID 35980387, 2022). "The role of FOXF1 in lung endothelial cells during pulmonary fibrosis is unknown." (PMID 37137915, 2023). "In the FOXF1-deleted mouse model, an increase in the switch from N-cadherin to cadherin-11, which is a critical step in the acquisition of the profibrotic phenotype, was observed, suggesting that FOXF1 inhibited pulmonary fibrosis by regulating the cadherin switch." (PMID 35359592, 2022). "The vital role of FOXF1 in the pathogenesis of IPF was later highlighted by the observation that loss of Foxf1 increased migration of pulmonary fibroblasts via facilitating CDH2-CDH11 cadherin switch and thus aggravated bleomycin-induced pulmonary fibrosis in mice." (PMID 32244228, 2020).
rhabdomyosarcoma (10 papers, 2016 to 2025). A rare aggressive malignant mesenchymal neoplasm arising from skeletal muscle. "In contrast, FoxF1 expression was increased in patched-associated tumors, such as basal cell carcinoma, medulloblastoma and rhabdomyosarcoma, underlying the importance of FoxF1 in aberrant Hedgehog signaling in human cancers." (PMID 26625197, 2016). "Mounting evidence highlights FOXF1’s oncogenic role in rhabdomyosarcoma (RMS), particularly in the alveolar subtype (ARMS), making it a promising therapeutic target." (PMID 40508013, 2025). "This is supported by a few reports, in which the expression of FOXF1 was increased in basal cell carcinoma, medulloblastoma, and rhabdomyosarcomas." (PMID 32370197, 2020). "Previously, FOXF1 has been shown to stimulate cell proliferation in lung endothelial cells and in rhabdomyosarcoma tumor cells." (PMID 30670377, 2019). "Foxf1 depletion in rhabdomyosarcoma cells increased levels of the CDK inhibitor Cdkn1a (P21Cip1), whereas Foxf1-overexpression reduced Cdkn1a levels." (PMID 28878348, 2017). "Mice bearing FoxF1-overexpressing or control rhabdomyosarcoma tumors were treated with cisplatin to induce DNA damage response." (PMID 26625197, 2016). "Co-localization of FoxF1 with FANCD2 was also observed in a subset of tumor cells located within cisplatin-treated rhabdomyosarcoma tumors." (PMID 26625197, 2016). "Furthermore, FOXF1 was found to be required for oncogenic potential of tumor cells in rhabdomyosarcomas and gastrointestinal stromal tumors." (PMID 38589650, 2024). "A nice AP-1-associated enhancer regulation motif based on FOXF1 might also be a model for the family member FOXO1, which is exposed in our study and is associated with Rhabdomyosarcoma." (PMID 30563222, 2018). "Interestingly, stable overexpression of FoxF1 in rhabdomyosarcoma cells was sufficient to increase FA protein levels in tumor tissue even in the absence of DNA damage (lanes 3–5)." (PMID 26625197, 2016). "Thus, FoxF1 increases the FA protein levels in tumor tissue in a mouse model of rhabdomyosarcoma." (PMID 26625197, 2016). "Milewski et al77 found that PAX3-FOXO1 fusion protein is a key oncogenic driver of rhabdomyosarcoma, and PAX3-FOXO1 knockdown reduced FOXF1 mRNA and protein expression in RH4 and RH18 FP-RMS cells, which in turn regulates the development of rhabdomyosarcoma." (PMID 40584293, 2025).